RN7SL488P (RNA, 7SL, cytoplasmic 488, pseudogene)
Gene: Miscellaneous RNA gene on chromosome 1 (63,529,613 to 63,529,898, reverse strand). Ensembl gene ENSG00000264271.
Homologues: Orthologues: macaque Metazoa_SRP (70% identical). Paralogues in human: RN7SL96P (82% identical), Metazoa_SRP (81% identical), RN7SL510P (81% identical), RN7SL774P (81% identical), RN7SL391P (81% identical), RN7SL622P (81% identical), RN7SL811P (81% identical), RN7SL134P (80% identical), RN7SL784P (80% identical), RN7SL123P (80% identical), Metazoa_SRP (80% identical), RN7SL163P (79% identical), and 707 more.